MTOR (mechanistic target of rapamycin kinase)
Diseases named in the same sentence as MTOR in open-access papers (continued):
Sharing a sentence is not in itself a finding about the gene and the disease.
cancer (continued). "The hallmarks of cancer pathway PI3K_AKT_MTOR and epithelial_mesenchymal_ transition were significantly enriched for A1 and A2, respectively, whereas the glycolysis and IL2_STAT5_oncogenic pathways were enriched for subgenotype D3 and genotype E, respectively." (PMID 39066215, 2024). "The abnormal activation of the mTOR pathway is believed to have significant implications for the proliferation of cancer cells and their resistance to anti-cancer drugs across various forms of cancer." (PMID 39204369, 2024). "These proteins are central to the PI3K/AKT/mTOR signaling pathway, a pathway frequently upregulated in cancer and involved in promoting cell growth, survival, and metabolism." (PMID 39770406, 2024). "Tumor cells and transformed cells with disrupted mTOR signaling are more sensitive to mTOR inhibitors than normal cells, making mTOR an important target for cancer treatment." (PMID 38717641, 2024). "Saponins have been reported to inhibit various signalling pathways, such as PI3K/AKT, AKT/MAPK, EGFR/PI3K/AKT, PI3K/AKT/mTOR, and RNF6/AKT/mTOR, which leads to its cytotoxic and apoptotic properties on various cancer cell lines." (PMID 39519799, 2024). "We explored combining rapamycin, a selective mTOR inhibitor with promising clinical trial outcomes for various cancers, with Ad.What." (PMID 39329778, 2024). "siRNA-targeting components of the mTOR pathway, such as mTOR itself or downstream effectors, can modulate ROS production in cancer and metabolic disorders." (PMID 39334768, 2024). "Because H2S gas is an important gas signalling transmitter, we can design a series of H2S donors that can target and kill cancer cells by modulating the PI3K/AKT/mTOR pathway." (PMID 39906126, 2024). "Studies suggested that the dysregulation of the PI3K/AKT/mTOR signalling pathway in cancer patients is mainly through HSPs and the UPS." (PMID 38543274, 2024). "In the context of HNC, the regulation of the PI3K/AKT and mTOR pathway is dysregulated, which can contribute to the development of various types of human cancers." (PMID 39469621, 2024). "Further, the activated mTOR pathway which results in phosphorylated 4EBP1 and S6K leads to higher levels of CyclinD1, while the inhibition of PI3K/AKT/mTOR/S6K leads to decreased CyclinD1 expression in cancer cells." (PMID 38611022, 2024). "PI3K/AKT/mTOR intricately engages with these factors, influencing the creation of a vascular network that facilitates the cancer cell's journey by ensuring a nutrient-rich and oxygenated environment." (PMID 39369580, 2024). "To date, there is sufficient evidence that various SeNPs are able to inhibit the PI3K/Akt/mTOR signaling pathway in various cancer cells." (PMID 38994955, 2024). "This review provides new insights into the patterns of mTOR functioning in quiescent cancer cells, enhancing our current understanding of the biology of latent metastasis." (PMID 38418814, 2024). "Metformin significantly reduces the levels of c-myc and Bcl-xl by stimulating AMPK to inhibit mTOR, thus inhibiting the metabolism and proliferation of cancer cells." (PMID 38286894, 2024). "mTOR signaling is frequently activated in cancer and plays critical roles in regulating the proliferation and metabolism of cancer cells." (PMID 39766137, 2024). "Mesothelin is overexpressed in solid tumors and plays a role in activating Akt/PI3K and mTOR signaling pathways, thereby promoting cancer cell proliferation and survival." (PMID 38396817, 2024). "This discrepancy in results means that how paclitaxel modulates the mTOR pathway needs to be discussed case by case according to different cancer types." (PMID 39584140, 2024). "Rapamycin is a common mTOR (mechanistic target of rapamycin) inhibitor in cancer because of its ability to hamper the development and division process of cells." (PMID 39772235, 2024).
cancer (continued). "This duality of autophagy function in cancer prevention and formation can be illustrated by the findings derived from the study using mTOR inhibitors in cancers." (PMID 38976168, 2024). "The mTOR pathway participates in multiple tumor cell processes, and hyperactivated mTOR signaling is observed in different types of cancers." (PMID 38763973, 2024). "By activating AMPK, metformin inhibits the mammalian target of rapamycin (mTOR) pathway, which is critical for cell growth and proliferation, thereby reducing protein synthesis and suppressing cancer cell growth." (PMID 39272875, 2024). "The downstream transcription factors of the mTOR signaling pathway (with the highest enrichment score) include HIF1α, c-Myc, FoxO, and other important cancer regulatory molecules." (PMID 38418940, 2024). "Several miRNAs, have been identified as regulators of mTOR signaling and have been found to modulate the response of cancer cells to radiation therapy." (PMID 38965615, 2024). "This therapy effectively inhibits the proliferation of HCC cells and suppresses tumor growth by targeting specific pathways involved in cancer progression, including mTOR, PAK4, RHOC, and EMT." (PMID 39273339, 2024). "Translational research findings, highlighting the mTOR axis’s effectiveness in cancer treatment, advocate for the development of precise preclinical models." (PMID 39595628, 2024). "Conversely, during nutrient starvation, mTOR activity decreases, leading to the induction of autophagy, which can provide metabolic substrates to sustain cancer cell survival and growth." (PMID 39512820, 2024). "Cancer frequently hyperactivates the PI3K/AKT/mTOR signaling pathway, which controls several cellular activities, including cell growth, proliferation, motility, survival, and apoptosis." (PMID 38384328, 2024). "Metformin decreased the expression of oncogenes, including those in the PI3K/mTOR pathway, as well as survival and cancer stem cells." (PMID 38474224, 2024). "It is critical for the efficient uptake of leucine and glutamine and then sends a regulatory signal to activate the mammalian target of rapamycin (mTOR), thereby supporting cancer cell proliferation, growth, and apoptosis resistance." (PMID 38987867, 2024). "The findings in this study are significant for the development of mTOR inhibitors, which have been developed and evaluated in clinical trials for various cancer types." (PMID 38671459, 2024). "As shown in the bubble plots, the downstream mRNAs of let-7a-5p were enriched in signaling pathways involved in cancer progression, i.e, mTOR signaling pathway, PI3K-AKT signaling pathway." (PMID 39868374, 2024). "mTOR is essential for maintaining mitochondrial respiratory capacity and plays a role in controlling cancer cell metabolism by regulating anabolic processes such as ribosome biogenesis and protein, nucleotide, fatty acid, and lipid synthesis." (PMID 38654380, 2024). "This variant has been previously identified in various cancers, predominantly in a somatic allele origin, and has been shown to result in the activation of the PI3K/AKT/mTOR pathway and oncogenic cell transformation." (PMID 39684472, 2024). "We have seen that PI3K, p-AKT, and p-mTOR proteins were significantly suppressed in cancer cells treated with SsnB compared to the control groups." (PMID 39770406, 2024). "The PI3K/AKT/mTOR pathway is one of the most common dysregulated pathways in cancer, and the PI3K/AKT/mTOR signaling pathway is closely related to tumor cell proliferation and angiogenesis." (PMID 39508039, 2024). "For example, aberrant activation of the PI3K/AKT/mTOR pathway promotes abnormal metabolism in cancer cells." (PMID 38962132, 2024). "AKT/mTOR signaling, a key axis in cancer development and a potential drug therapeutic target, can induce cell proliferation at different stages of cell development." (PMID 38482052, 2024).
cancer (continued). "Rubioncolin C induced apoptosis of cancer cells and autophagy-related death, while inhibitng the Akt/mTOR/p70S6K signaling pathway." (PMID 38668684, 2024). "Analysing these diagrams confirms the mTOR involvement in producing high energy levels in hypoxic cancer cells, as impeding its activity drove the cell towards a similar energy level produced in our hypoxic normal cells." (PMID 39207627, 2024). "We also examined the DEGs enriched in metabolic signaling pathways, specifically the AMPK and mTOR, which are known to be interconnected key regulators of cancer cell metabolism." (PMID 38489280, 2024). "In conclusion, CD133 plays a crucial role in the increased activation of the PI3K/AKT/mTOR pathway in cancer cells, thereby contributing to their aggressive behavior and resistance to therapies." (PMID 39456981, 2024). "The PI3K/AKT/mTOR pathway is also involved in cancer-promoting features such as angiogenesis and inflammatory cell recruitment." (PMID 38672069, 2024). "mTOR is known to be abnormally activated in cancers as it plays an important role in regulating metabolism." (PMID 38358644, 2024). "Because mTOR signaling plays a crucial role in sustaining cancer survival, drugs that target this signaling pathway have achieved significant anticancer effects in the clinic." (PMID 39513392, 2024). "Apoptosis in cancer cells has been discovered to be mediated by the signaling pathway proteins PI3K/AKT/mTOR." (PMID 38527038, 2024). "PA, a key intermediate in the Kennedy pathway for de novo phospholipid biosynthesis, has been shown to be necessary for the stabilization and activation of mTOR complexes and that PA containing OA results in robust activation of mTOR in cancer cell lines." (PMID 38223199, 2024). "Dormant cancer cells with inhibited mTOR activity appears to be in a state of stable reversible hibernation, while active mTOR subunit indicates a temporary cell cycle arrest or senescence." (PMID 38418814, 2024). "mTOR has a close relationship with cancer given that it has implications in the control of several essential processes such as cell cycle, proliferation, growth and survival as well as protein synthesis and glucose metabolism." (PMID 38539200, 2024). "mTOR is a protein involved in cell cycle progression and regulation, and therefore drives cells to divide, including cancer." (PMID 38533302, 2024). "It is well known that PI3K/AKT/mTOR signaling pathway plays a crucial role in cancer cell proliferation, survival, metastasis and angiogenesis, and AKT and mTOR are both downstream targets of VEGFA." (PMID 38429756, 2024). "One of these is the PI3K/AKT/mTOR signaling pathway, which serves a major role in cancer cell growth and tumor proliferation by responding to different types of factors such as nutrients, hormones and growth factors." (PMID 39301125, 2024). "This is exemplified by studies that showed that artesunate treatment in cancer models mitigates the Wnt pathway, the phosphoinositide-3 kinase/protein kinase B/mTOR pathway, as well as their downstream targets." (PMID 38282649, 2024). "Beyond its significance in OP, the mTOR pathway’s role is profoundly critical in bone metastases and the wider sphere of cancer, underscoring the urgent need for in-depth research to unlock the full therapeutic promise of mTOR modulation." (PMID 39595628, 2024). "An increase in PA after OA treatment has been shown to activate mTOR signaling in cancer cell lines and knockdown of AGPAT2 expression prevented the effect, suggesting that OA, when incorporated into PA, was a potent stimulator of mTOR activity." (PMID 38223199, 2024). "Protein translation anomalies induced by mTOR pathway dysregulation are observed in different kinds of cancer." (PMID 39162964, 2024).
cancer (continued). "Our transcriptomic analyses demonstrate that cell lines weakly responsive to the combination treatments exhibited higher expression of genes in cancer hallmark pathways, such as EMT, PI3K/AKT/mTOR signaling and TGFβ signaling." (PMID 39103541, 2024). "Up to now, the FDA has already approved the allosteric inhibitors of mTOR, everolimus, and temsirolimus for the treatment of advanced cancers of the kidney, breast, and pancreas." (PMID 38339341, 2024). "Inhibition of the PI3K/AKT/mTOR signaling pathway has emerged as a significant approach to sensitizing cancer cells to Ferroptosis, a novel pathway of programmed cell death." (PMID 39399463, 2024). "This activation of PI3K/AKT/mTOR pathway plays crucial roles in cancer progression and survival, particularly during cell invasion and migration." (PMID 37921969, 2024). "The use of mTOR inhibitors can mitigate EMT characteristics and cancer stem cell properties induced by FBXW7 mutations." (PMID 39749199, 2024). "The crosstalk between mTOR signaling and miRNAs in cancers has emerged as a significant area of research." (PMID 38965615, 2024). "Metformin has been shown to have a dual role in the treatment of type 2 diabetes and cancers by regulating mTOR signaling." (PMID 38892329, 2024). "The KEGG pathway indicated that the differentially expressed proteins were mainly involved in EGFR tyrosine kinase inhibitor resistance, FoxO signaling central carbon metabolism in cancer, and the mTOR signaling pathway." (PMID 39335579, 2024). "In particular, NOTCH2 H107P and BCR T1127S variants were almost clonal (i.e., present in all somatic cells), whereas EPHA7 L564F and MTOR S920F were subclonal alterations, present in around 35% of cancer cells." (PMID 39421445, 2024). "Manipulating mTOR signaling offers a promising strategy for enhancing cancer cell phagocytosis, paving the way for innovative macrophage-based therapeutic approaches." (PMID 39766137, 2024). "The fact that 28 decreased the expression levels of p-AKT and p-mTOR indicated its ability to inhibit the P13K/AKT/mTOR-signaling pathway, an intracellular pathway important in cell cycle regulation and directly related to cell proliferation and cancer." (PMID 39202963, 2024). "High insulin levels activate the PI3K/Akt/mTOR signaling pathway promoting cancer cell growth, survival, proliferation, metastasis, and anti-apoptosis." (PMID 39410536, 2024). "LAT1 is widely expressed in human neoplasms and supplies the essential amino acids to enhance the growth of cancer cells via mammalian target-of-rapamycin (mTOR) stimulated translation." (PMID 39290273, 2024). "Considering the mTOR inhibitor is used as an immunosuppressant drug as well as an anti-cancer drug, the low serologic response is expected." (PMID 38381163, 2024). "Consistent with our observations, numerous other studies have investigated the effects of PI3K/Akt and mTOR inhibitors on cancer progression, further supporting the significance of Akt and mTOR inhibition in mediating the observed effects of CLs." (PMID 38672078, 2024). "A previous study showed that ABHD5 activated the AMPK signaling pathway to suppress the mTOR signaling pathway, leading to the suppression of cancer cell anabolism." (PMID 39093497, 2024). "Recent investigations indicate mTOR signaling inhibition to be a central node for the transition of stem cells and, in particular, cancer cells to a quiescent state." (PMID 38418814, 2024). "PI3K/AKT/mTOR is one of the most common regulatory pathways in malignant tumors, affecting cell proliferation, migration, and metastasis." (PMID 39608715, 2024). "The mTOR inhibitor Rapamycin was shown to exert its anti-cancer effect by perturbing this mTOR/NEAT1-mediated mechanism." (PMID 38203767, 2024). "We observed significant differences in the expression of mTOR and Beclin genes between cancer and normal groups, indicating the possibility of autophagy activation in cancerous samples." (PMID 38164366, 2024).
cancer (continued). "KEGG results showed that the "PI3K-Akt signaling pathway", "mTOR signaling pathway", "PD-L1 expression and PD-1 checkpoint pathway in cancer" and "T cell receptor signaling pathway" were significantly enriched." (PMID 39494327, 2024). "Downregulation of ERK1/2 and upregulation of the JNK pathways due to CP/PAL are usually accompanied with decreased PI3K/Akt/mTOR pathway and downstream NFκB activity in cancer cells to inhibit proliferation and promote caspase 9/3-dependent apoptosis." (PMID 38785562, 2024). "Targeting the PI3K/Akt/mTOR pathway has become a promising cancer treatment strategy, with several drugs in development and testing showing potential in preclinical and clinical studies." (PMID 38994962, 2024). "In response, a diverse array of mTOR inhibitors has been crafted and is currently under clinical investigation, with several already securing approval for cancer treatment." (PMID 39595628, 2024). "PI3K/mTOR is an essential intracellular signaling pathway for cancer cell survival, regulation of cell proliferation and tumor growth." (PMID 40115434, 2024). "Interactions between MM cells and stromal cells activate the PI3K/AKT/mTOR pathway, which initiates a signaling cascade that promotes resistance to chemotherapy and cancer progression." (PMID 38634972, 2024). "For the cancer-inhibition mechanism, the authors specifically excluded possible pathways of mTOR or methylglyoxal toxicity by increased G3P and, instead, proposed the inhibition of mitochondrial respiration and ATP generation by G3P." (PMID 38689091, 2024). "The development of dual signaling pathway inhibitors targeting PI3K/AKT/mTOR and other pathways is underway to enhance cancer therapy." (PMID 38398072, 2024). "LAT1 is related to various types of cancer (hyperactivation of mTOR through AA excess) and other diseases." (PMID 39198298, 2024). "By integrating its functions in nutrient signaling and gene expression related to growth and metabolism, nuclear mTOR emerges as a central hub governing cellular homeostasis, malignant transformation, and cancer progression." (PMID 38727317, 2024). "Inhibitors targeting this pathway, such as rapamycin (an mTOR inhibitor), have been explored as potential cancer therapies." (PMID 39483536, 2024). "By selectively targeting mTOR in CSCs, this therapeutic strategy offers an advanced approach to anti-cancer treatment, aiming to achieve efficacy while minimizing off-target effects on non-CSC populations." (PMID 39349424, 2024). "Stigmasterol mitigates inflammation through the suppression of the NF-κB signaling pathway and impedes cancer cell proliferation and survival by targeting the Akt/mTOR and JAK/STAT pathways." (PMID 39712495, 2024). "CARMN exerts an anti-cancer effect in CC progression by inhibiting the Akt-mTOR and MAPK signaling pathways." (PMID 39558374, 2024). "Given that the PI3K-AKT pathway leads to the activation of mTOR, and the mTOR pathway is disrupted in cancer, it is interesting for us to discuss the drug Rapamycin in the context of these and other pathways, as it holds elucidations on our theory." (PMID 39981299, 2024). "Abnormal activation of the PI3K/AKT/mTOR signaling pathway leads to the occurrence and progression of human cancers." (PMID 39748950, 2024). "The PI3K/AKT/mTOR signaling pathway has been extensively researched and has been proven vital for RT resistance in several cancer types." (PMID 38474604, 2024). "The central role of PI3K/AKT/mTOR signaling in many types of cancer has spurred research in that direction with different classes of such inhibitors currently being tested in clinical trials." (PMID 38747293, 2024).